DNAH17 (dynein axonemal heavy chain 17)
Description:
Force generating protein component of the outer dynein arms (ODAs) in the sperm flagellum (By similarity). Produces force towards the minus ends of microtubules (By similarity). Key component of dynein, a family of motor proteins essential for movement along microtubules (By similarity). Dynein has ATPase activity; the force-producing power stroke is thought to occur on release of ADP (By similarity). Required for structural and functional integrity of cilia (By similarity). Plays a major role in sperm motility, implicated in sperm flagellar assembly and beating.
Synonyms: DNAHL1; DNEL2; FLJ40457; SPGF39
Tractability: PROTAC: ubiquitination databases record sites on it.
Gene: Protein-coding gene on chromosome 17 (78,423,697 to 78,577,396, reverse strand). Ensembl gene ENSG00000187775.
Subcellular location: Cytoplasm, cytoskeleton, flagellum axoneme; Cell projection, cilium, flagellum
Subcellular location (Human Protein Atlas): End piece; Mid piece; Principal piece
Gene Ontology:
Molecular function: dynein intermediate chain binding; dynein light intermediate chain binding; microtubule motor activity; minus-end-directed microtubule motor activity; ATP binding
Biological process: outer dynein arm assembly; cilium movement involved in cell motility; cilium-dependent cell motility; microtubule-based movement; microtubule-based process
Cellular component: axoneme; outer dynein arm; sperm end piece; sperm flagellum; sperm midpiece; sperm principal piece; 9+2 motile cilium; axonemal dynein complex; dynein complex; motile cilium
Genetic constraint (gnomAD): Loss-of-function variants: 370 observed, 469.28 expected, observed/expected ratio (o/e) 0.79, 90% interval 0.72 to 0.86. The synonymous counts are far from expectation, so gnomAD's model fits this gene poorly and the ratio says little. Missense variants: 6,308 observed, 5,892.2 expected, observed/expected ratio (o/e) 1.07, 90% interval 1.05 to 1.09. Synonymous variants: 3,003 observed, 2,433.9 expected, observed/expected ratio (o/e) 1.23, 90% interval 1.2 to 1.27.
Gene-disease validity (ClinGen):
ClinGen rates the evidence that DNAH17 causes each of these diseases.
spermatogenic failure 39 (autosomal recessive): Definitive.
Homologues: Orthologues: chimpanzee DNAH17 (99% identical), rat Dnah17 (92% identical), mouse Dnah17 (91% identical), guinea pig DNAH17 (91% identical), dog DNAH17 (91% identical), pig DNAH17 (89% identical), rabbit DNAH17 (67% identical). Paralogues in human: DNAH9 (63% identical), DNAH11 (59% identical), DNAH2 (31% identical), DNAH10 (31% identical), DNAH5 (29% identical), DNAH8 (29% identical), DNAH6 (28% identical), DNAH7 (28% identical), DNAH1 (28% identical), DNAH3 (27% identical), DNAH12 (27% identical), DNAH14 (23% identical), and 3 more.
Diseases named in the same sentence as DNAH17 in open-access papers:
DNAH17 is named in the same sentence as 27 diseases in open-access papers, as found by Europe PMC text mining. Sharing a sentence is not in itself a finding about the gene and the disease. The quoted sentences say what the papers report.
male infertility (13 papers, 2020 to 2024). The inability of the male to effect fertilization of an ovum after a specified period of unprotected intercourse. "Damage in the integrity of microtubule doublet structure has been shown to be associated with sperm motility defects and male infertility, as seen for the deletion of Ccdc176, Tmem232, Cfap97d1, Dnah17, Trll9, Pla2g3 and Vdac3 in mice." (PMID 38750428, 2024). "Loss of function mutations in DNAH17 are linked to a genetically heterogeneous disorder leading to male infertility and multiple morphological abnormalities of the flagella (MMAF)." (PMID 39769462, 2024). "Currently, 13 members of the DNAH gene family have been reported, including DNAH1 to DNAH3, DNAH5 to DNAH12, DNAH14, and DNAH17, among which 11 genes (DNAH1, DNAH2, DNAH5 to DNAH12, and DNAH17) are associated with male infertility." (PMID 38312775, 2024). "In humans, there are 13 dynein axonemal heavy chain (DNAH) proteins (DNAH1–3, DNAH5–12, DNAH14, and DNAH17) and mutations in many of these genes have been associated with male infertility." (PMID 36140773, 2022). "In the literature isolated male infertility and asthenozoospermia is described in individuals with variants in DNAH17." (PMID 35474353, 2022). "Studies using mouse models revealed that deletion of Ttll9, Vdac3, Dnah17, or Cfap97d1 resulted in the instability of sperm microtubule doublets 4–7, associated with sperm motility defects and male infertility." (PMID 34759295, 2021). "Additionally, other DNAHs, such as DNAH1, DNAH2, DNAH8, DNAH10, DNAH12, and DNAH17, are suggested to be pathogenic genes of isolated male infertility." (PMID 39503742, 2024). "Similarly, deletion of Vdac3, Pla2g3, and DNAH17 caused instability of sperm microtubule doublets 4–7, associated with sperm motility defects and male infertility." (PMID 32785227, 2020). "Mutations in two IDA heavy-chain protein-encoding genes, DNAH1 (MIM: 603332) and DNAH2 (MIM: 603333), and two ODA heavy chain components, DNAH8 (MIM: 603337) and DNAH17 (MIM: 610063), have been described in individuals with isolated male infertility due to asthenoteratozoospermia." (PMID 37424858, 2023). "For example, mutations in DNAH17 (β-heavy chain of ODA) have been reported to be associated with poor sperm motility and male infertility, with no observed effects in respiratory cilia." (PMID 34233705, 2021).
Infertility (8 papers, 2020 to 2026). "However, two novel compound heterozygous mutations within the DNAH17 gene were identified using whole exome and Sanger sequencing in an infertile man with markedly diminished sperm motility and caused TFF after two ICSI attempts." (PMID 36589837, 2022). "It remains elusive whether the variants in DNAH17 may cause infertility in GL-3." (PMID 31985809, 2020). "We applied this framework to generate gene-specific protocols for two men in whom infertility was caused by the respective disruption of the genes MEI1 and DNAH17." (PMID 41863311, 2026). "It has been demonstrated that infertile males with variants in DNAH1, DNAH2, DNAH7, and DNAH8 have a favorable prognosis, while patients with variants in DNAH17 have poor outcomes after ICSI treatment." (PMID 39503742, 2024). "Taken together, our research identified compound heterozygous DNAH17 variants (c.4109C>T and c.9776C>T; c.612C>G and c.8764C>T) in families with LR asymmetry disorders, typical phenotypes of ciliary disorders, including SIT, dextrocardia, and CHD, albeit infertility cannot be excluded." (PMID 35692830, 2022).
asthenozoospermia (7 papers, 2020 to 2024). "For example, Dnah17, Vdac3, and Pla2g3 loss induces destabilization of sperm MTDs 4–7, causing asthenozoospermia, whereas Ccdc176 KO mouse sperm exhibit axonemal structure deficiency in the absence of Dmt1 and/or 9 (missing Dmt1, Dmt9, or both)." (PMID 39516485, 2024). "We report for the first time a possible association between DNAH17 gene variants and left–right asymmetry disorders, which is known as a causal gene for asthenozoospermia." (PMID 35692830, 2022). "Whole-exome sequencing identified a missense variant (c.G5408A, p.C1803Y) in DNAH17, a functionally uncharacterized gene, recessively cosegregating with asthenozoospermia in the family." (PMID 31658987, 2020). "In conclusion, we demonstrated that a homozygous DNAH17 missense variant specifically induces MTDs 4–7 destabilization in cauda epididymis, resulting in asthenozoospermia." (PMID 31658987, 2020). "Combined with the reported DNAH17-associated asthenozoospermia, we proposed that DNAH17 compound heterozygous variants, or homozygous variants, may potentially cause a specific disease, the DNAH17-associated ciliary/flagellar disorder." (PMID 35692830, 2022). "Recently, mutations in DNAH17 were identified in patients with asthenozoospermia." (PMID 31985809, 2020). "Hence, consistent with the findings in the patients, Dnah17M/M mice displayed markedly diminished sperm motility, proving that the DNAH17 variant is indeed pathogenic for asthenozoospermia." (PMID 31658987, 2020). "Due to a common highly conserved 9+2 axonemal structure of cilia and sperm flagella, different DNAH17 mutations may independently cause flagella destabilization, asthenozoospermia or LR asymmetry disorders in specific organelle sharing a common axonemal machinery." (PMID 35692830, 2022). "Subsequent Sanger sequencing on genomic DNA from all the available family members (III:1, III:2, and IV:1–7) verified four variants in four genes (DNAH17, GPS1, HID1, and USP36) recessively coinherited with asthenozoospermia." (PMID 31658987, 2020). "Variations in the dynein axonemal heavy chain 17 gene (DNAH17, OMIM 610063), encoding a component of outer dynein arms (ODAs) in the ciliary axonemes, have been reported to be associated with only flagella destabilization and asthenozoospermia." (PMID 35692830, 2022). "There are, however, comparatively fewer studies that have investigated DNAH17 and multiple morphological abnormalities of the flagella and asthenozoospermia, perhaps limited by the number of LR asymmetry phenotype-associated patients; further research is needed." (PMID 35692830, 2022). "In addition, the current knowledge on the crucial part of DNAH17 playing in flagella destabilization and asthenozoospermia may depend on genetic or environmental factors such as the mutation type, organism or context." (PMID 35692830, 2022). "Previous reports had revealed that the biallelic mutations of DNAH17 in human sperm were associated with impaired motility and multiple morphological abnormalities of the flagella (MMAF), a rare type of asthenozoospermia which is characterized by absent, short, bent, coiled, and irregular flagella." (PMID 36589837, 2022).
Globozoospermia (2 papers, 2020 to 2024). Any structural anomaly of the acrosome resulting in a round sperm head. "It remains uncertain whether variants in DNAH17 or MAGEA3 cause globozoospermia." (PMID 31985809, 2020).
hepatocellular carcinoma (2 papers, 2019 to 2024). A malignant tumor that arises from hepatocytes. "This interesting finding encouraged us to explore the potential relationship between DNAH17 and hepatocellular carcinoma." (PMID 30575322, 2019). "Overexpression of DNAH17 by downregulation of methylation levels might contribute to hepatocellular carcinoma (HCC) initiation and progression." (PMID 38724875, 2024).
hypospadias (2 papers, 2025). Hypospadias is the displacement of the urethral meatus on the ventrum of the penis. "Notably, COL6A3 expression has been reported to be upregulated in DNAH17 mutants associated with severe hypospadias, suggesting a possible link that merits closer examination." (PMID 41300791, 2025). "However, COL6A3 gene expression was upregulated in DNAH17 mutants detected in severe hypospadias and therefore requires further assessment." (PMID 41300791, 2025). "There were no observed phenotypes of hypospadias or reduced penile development, which was consistent with previous studies showing that male mice heterozygous or homozygous for the DNAH8, DNAH9, and DNAH17 pathogenic mutations did not have the hypospadias phenotype." (PMID 41463044, 2025).
blepharospasm (1 paper, 2019). "Interestingly, a recent study showed that deleterious variants in CACNA1A, REEP4, TOR2A, ATP2A3, HS1BP3, GNA14, and DNAH17 were involved in blepharospasm, and none of these variants except for CACNA1A has been reported to be associated with blepharospasm." (PMID 32038460, 2019).
bronchiectasis (1 paper, 2022). Segmental, irreversible dilation of the bronchial tree resulting in the accumulation of secretions which leads to obstruction. "The lack of typical symptoms, such as nasosinusitis and bronchiectasis, in the two patients may be due to absent or low expression of DNAH17 in specific tissues after the completion of the embryonic development." (PMID 35692830, 2022).
cardiomyopathy (1 paper, 2021). A disease of the heart muscle or myocardium proper. "However, DNAH17 and DNAH8 mutations have been clinically implicated in spermatogenic failure [OMIM: 618643] and have never been reported in association with cardiomyopathy." (PMID 34387706, 2021).
Cirrhosis (1 paper, 2019). A chronic disorder of the liver in which liver tissue becomes scarred and is partially replaced by regenerative nodules and fibrotic tissue resulting in loss of liver function. "The HCC samples with liver cirrhosis had lower DNAH17 methylation levels than those without liver cirrhosis (non‐cirrhosis vs cirrhosis, 73% vs 64%, P = 0.0047)." (PMID 30575322, 2019).
liver cancer (1 paper, 2024). An epithelial or non-epithelial malignant neoplasm that arises from the liver. "Aberrant methylation of dynein axonemal heavy chain 17 (DNAH17) is associated with comprehensive clinic-pathological factors and can serve as a potential biomarker for tumor thrombosis in liver cancer patients." (PMID 38374893, 2024).
liver cirrhosis (1 paper, 2019). "Therefore, we speculated that DNAH17 is not only associated with liver cirrhosis, but also plays a more important role in oncogenesis under the liver cirrhosis background." (PMID 30575322, 2019).
Parkinson disease (1 paper, 2024). A progressive degenerative disorder of the central nervous system characterized by loss of dopamine producing neurons in the substantia nigra and the presence of Lewy bodies in the substantia nigra and locus coeruleus. "Two Parkinson’s disease risk genes presented distinct patterns, with PLPP4 expressed in initial OPC cells and DNAH17 expressed in late oligodendrocytes." (PMID 39363111, 2024).
Sepsis (1 paper, 2024). Sepsis is defined as life-threatening organ dysfunction caused by a dysregulated host response to infection. "H-MDSCs also share substantial overlap with M-MDSCs, with higher expression in sepsis of genes like S100A8/9 and DNAH17." (PMID 38720891, 2024).
Situs inversus totalis (1 paper, 2022). "Dynein axonemal heavy chain 17 (DNAH17) is a protein of the DNAH family of which four genes have already been associated with autosomal recessive PCD, situs inversus totalis or heterotaxy, namely DNAH1, DNAH5, DNAH9, and DNAH11." (PMID 35474353, 2022).
Tourette syndrome (1 paper, 2023). A neurologic disorder caused by defective metabolism of the neurotransmitters in the brain. "Variants in DIP2C (disco interacting protein 2 homolog C) and DNAH17 (dynein axonemal heavy chain 17) have been previously linked to ASD, and WWC1 was identified as a risk gene for Tourette syndrome, another NDD known to be comorbid with ASD." (PMID 37686052, 2023).
virus infection (1 paper, 2022). "DEGs such as cytosolic carboxypeptidase 3, dual-specificity protein phosphatase 10, 15, dynein axonemal heavy chain 17, fasciclin 2, inhibin beta chain, replication factor A protein 1, and Tob1 were found enriched and favored the virus infection and circulation in B. tabaci." (PMID 35572639, 2022).
tumor (7 papers, 2019 to 2025). "The discriminatory capacity of DNAH17 methylation levels was evaluated to distinguish HCC patients with tumor thrombus through ROC curve analysis." (PMID 30575322, 2019). "Contrarily,both RNA‐seq and immunohistochemistry indicated the expression of DNAH17 was increased in tumor tissues (P < 0.05)." (PMID 30575322, 2019). "Receiver operator characteristic (ROC) curve analysis demonstrated the methylation levels of DNAH17 could efficiently predict the existence of the fibrous capsule (AUC = 0.695) and tumor thrombus (AUC = 0.806)." (PMID 30575322, 2019). "Our result indicated that the methylation status of DNAH17 was a promising biomarker for tumor thrombosis, which could provide more information about HCC features in the preoperative biopsy and help clinicians generate an individual treatment strategy." (PMID 30575322, 2019). "Here, we found that HCC patients with tumor thrombus were always accompanied by hypomethylation of DNAH17 in the promoter of isoform 2, which implied that down‐regulated methylation of DNAH17 might promote HCC metastasis." (PMID 30575322, 2019). "In addition, the hypomethylation status of the DNAH17 gene, both in tumor tissue and adjacent non‐cancerous tissue, could be a promising biomarker for tumor thrombosis in HCC." (PMID 30575322, 2019). "Among the distinctively upregulated genes in low EGF treatment, we found genes related to anti-tumor immunity, sperm flagellar assembly, and mitogenesis (SLC6A6, DNAH17, DUOX1)." (PMID 39694501, 2025). "We found 11 of 20 pairs of HCC samples (55%) presented high expression of DNAH17 in the tumor tissues compared with ANT, and DNAH17 expression in HCC tissues was significantly higher than ANTs in most of HCC samples (P = 0.0058)." (PMID 30575322, 2019). "Although there have been prior reports of abnormal expression of DNAH17 and SSPO genes in tumors, there is a lack of systematic research of the association between these abnormalities and outcomes of anti-tumor therapy." (PMID 34900698, 2021). "ROC curve analysis showed that hypomethylation status of DNAH17 in HCC patients could be a biomarker to predict the existence of fibrous capsule and tumor thrombus." (PMID 30575322, 2019). "In addition, the hypomethylation status of the DNAH17 gene, both in tumor tissue and in adjacent non-cancerous tissue, could be a promising biomarker for tumor thrombosis in HCC." (PMID 38724875, 2024). "Our findings showed that the hypomethylation status of DNAH17 in both tumor tissues and adjacent non‐cancerous tissues could help discriminate HCC patients with tumor thrombus from those without tumor thrombus." (PMID 30575322, 2019).
infection (1 paper, 2022). The state of being infected such as from the introduction of a foreign agent such as serum, vaccine, antigenic substance or organism. "Upregulation of DNAH17 and AGBL3 post-ChiLCV exposure in the present study might be due to the manipulation of B. tabaci genes by ChiLCV to facilitate the infection and circulation of the virus within the vector." (PMID 35572639, 2022).
neurological disease (1 paper, 2018). "DNAH17 has not yet been linked to any other neurological or non‐neurological disease." (PMID 29770609, 2018).
DNAH17 also shares sentences with these, for which no sentence is quoted: cancer (1 paper); Dextrocardia (1); eosinophilia (1); liver diseases (1); ovarian carcinoma (1); spermatogenic failure (1); varicocele (1).